IL1B (interleukin 1 beta)
Diseases named in the same sentence as IL1B in open-access papers (continued):
Sharing a sentence is not in itself a finding about the gene and the disease.
COVID-19 (continued). "Among the proinflammatory cytokines (IL-1β, TNF-α, IL-8, and IL-6) analyzed herein, TNF-α was seen as a risk factor for the death of patients with severe or critical COVID-19." (PMID 34725309, 2021). "Given the propensity for systemic IL-1β, TNFα, and IL-6 to contribute to peripheral and central neuronal sensitization, it can be hypothesized that the increased prevalence of neurological manifestations seen in severe COVID-19 may be associated with elevations of these cytokines." (PMID 33458558, 2021). "In terms of laboratory parameters, elevated inflammatory cytokines and infection-related factors, such as TNF-α, IL-6, IL-10, IL-8, IL-1β, IL-2R, ferritin, hs-CRP and procalcitonin were significantly associated with higher death risk of COVID-19." (PMID 34521370, 2021). "Elevated NET values were shown in the blood of COVID-19 patients, and the released NETs further induce macrophages to release IL-1β, where cooperated action of NETs and IL-1β lead to excessive damage on pulmonary endothelium." (PMID 34372552, 2021). "IL-1B is activated in severe COVID-19, inducing vasodilation and permeability and providing the conditions for immune cells to arrive at the sites of damage." (PMID 34394108, 2021). "AIFA has also recently approved the compassionate use of canakinumab, a fully human monoclonal antibody that neutralizes the bioactivity of human IL-1β, in patients with COVID-19 (April 10, 2020)." (PMID 32547788, 2020). "Patients suffering from severe coronavirus disease 2019 (COVID-19) show highly elevated levels of Gal-3, TNFα, IL-1β, and IL-6, as compared to those with moderate disease (De Biasiet al., 2020;Wanget al., 2020a)." (PMID 33082935, 2020). "We conclude that in severe COVID-19 initial innate responses, primarily type I interferon, are suppressed or sabotaged which results in an early interleukin (IL)-6, IL-10 and IL-1β-enhanced hyperinflammation." (PMID 34192268, 2020). "In Castleman disease, IL-6 is elevated in conjunction with TNFα, IL-1β and IL-10 as in severe COVID-19; however, vascular manifestations are unusual in this condition." (PMID 32629875, 2020). "In contrast, patients with COVID-19 demonstrated activation of both Th1 and Th2 immunity, culminating inexpression of IFNγ, IL-1β, IL-4, and IL-10." (PMID 32742855, 2020). "COVID-19 generates a general increase in inflammatory cytokines, such as IL-1β and IL-6, and a mortality rate of 7.5%." (PMID 32973818, 2020). "The NLRP3 inflammasomes and IL-1β driven proinflammatory cascades correlate with worsening of several respiratory diseases, including COVID-19." (PMID 33160363, 2020). "COVID-19 increases the plasmatic secretion of interleukin 1β (IL-1β), interferon-γ (IFN-γ), interferon-γ-induced protein 10 kDa (IP-10), monocyte chemoattractant protein-1 (MCP-1), IL-4, and IL-10." (PMID 32635302, 2020). "In the current study, we demonstrated that severe COVID-19 is characterized by TNF/IL-1β-inflammatory features combined with the IFN-I response." (PMID 32651212, 2020). "Among 41 hospitalized COVID-19 patients in Wuhan, China, all had elevated IL-1B, IP10/CXCL10, and MCP1/CCL2." (PMID 32545518, 2020). "In other hand, recent studies have evaluated the use of Anakinra as a therapeutic strategy focused in signaling inhibition of IL-1β to treat COVID-19 related cytokine storm." (PMID 33193349, 2020). "Recent clinical investigation reveals that COVID-19 mild patients had high level of IL1B, IFNγ, CXCL10/IP-10 and CCL2/MCP-1, while patients requiring ICU admission had higher level of GCSF, CXCL10/IP-10, CCL2/MCP-1 and CCL3/MIP-1A." (PMID 32228226, 2020). "ARDS was evident in severe complications experienced by COVID-19 patients in China admitted to intensive care units, where the specific involvement in reducing cytokines IL-1β and IL-6 production is a strategy for COVID-19 intervention." (PMID 33233560, 2020). "Other reports have highlighted the usage of anti-TNF and anti-IL-1β to regulate inflammation in COVID-19 patients." (PMID 33072624, 2020).
COVID-19 (continued). "Polymorphonuclear (PMN)-MDSC expanded during COVID-19, in particular in patients who required intensive care treatments, and correlated with IL-1β, IL-6, IL-8, and TNF-α plasma levels." (PMID 33110074, 2020). "When we compared the immune responses from patients with mild and severe COVID-19 infections, we found that classical monocytes from severe COVID-19 exhibit IFN-I-driven signatures in addition to TNF/IL-1β-driven inflammation." (PMID 32651212, 2020). "In resting conditions, only IL-1β, IL-6, and IL-10 were detected in supernatants and showed similar levels between COVID-19 patients and healthy controls." (PMID 33634100, 2020). "As a strong induction of IL-1β has been observed in severely ill COVID-19 patients, the potential use of anakinra deserves further investigation." (PMID 33013675, 2020). "The discovery that IL-1B is upregulated by both smoking and COVID-19 suggests the possibility that inflammasomes are activated." (PMID 32752138, 2020). "Inflammatory cytokines IL1β, IL6, IL8, and TNFα associated with cytokine storm were significantly increased in the plasma of moderate and severe COVID-19 patients (p < 0.0001 for all cytokines)." (PMID 33585507, 2020). "In this regard, the activation of the inflammasome is also possible to occur during SARS-CoV-2 infection, as high levels of IL-1β have been observed in COVID-19 patients." (PMID 33013675, 2020). "Observed in MERS, SARS-CoV-1, and COVID-19 patients it is understood that initially delayed but gradual increase of IL-1β complicates patient's condition." (PMID 33634060, 2020). "ICU-COVID-19 patients had the highest concentrations of IL-1β, IL-6, IL-6 to IL-10 ratio, and tumor necrosis factor receptor superfamily member 1A (TNFR1)." (PMID 33142828, 2020). "SARS-CoV-2 spike protein can induce IL-8, IL-6 and TNF-α secretion in monocyte-derived macrophages (MDMs) and specifically primes COVID-19 patient-derived MDMs for IL-1β production in vitro." (PMID 34192268, 2020). "In the current study, we confirmed the results from previous studies by showing that the TNF/IL-1β inflammatory response is dominant in COVID-19 although a small number of patients were enrolled." (PMID 32651212, 2020). "High levels of interleukin IL-1β and IL-6 were detected in autopsy tissues from SARS-CoV patients and single cell RNA-seq analysis of peripheral blood in COVID-19 patients show increased subsets of CD14+ IL-1β-producing monocytes." (PMID 32655582, 2020). "Anti-malarial drugs hydroxychloroquine and chloroquine that are know to decrease Th17-related cytokines; IL-6, IL-17, IL-22, TNFα and IL-1β have been evaluated for efficacy in COVID-19 treatment in several clinical trials." (PMID 33708109, 2020). "We found that COVID-19 patients had a greater abundance ofCD14++ IL1β+ monocytesand IFN-activated monocytes than the HCs." (PMID 32377375, 2020). "COVID-19, like other CoV infections, causes ALI with high viral titers, high levels of the inflammatory cytokines IL-1β and IL-6 as well as infiltration of macrophages and neutrophils into the lungs." (PMID 33149733, 2020). "It has been well demonstrated that COVID-19 patients exhibited elevated inflammatory cytokines such as IL-1β, IL-6 and TNF-α in their serum." (PMID 33172355, 2020). "Of the proinflammatory cytokines, the following are of particular interest: CCL20, which has been associated with the first severe acute respiratory syndrome coronavirus (SARS-CoV), and IL-1B, CXCL1, CXCL2, and CXCL8, which are associated with COVID-19." (PMID 32752138, 2020). "Conversely, an increased TNF/IL-1β-driven inflammatory response was observed in severe COVID-19 patients as compared to severe influenza, and to mild COVID-19 patients." (PMID 33129318, 2020). "Although the knowledge on this inflammasome molecular process is continuously increasing, the temporal contribution of inflammasome-induced IL-1β to viral clearance and/or COVID-19 severity remains to be investigated." (PMID 33003552, 2020).
COVID-19 (continued). "Evidence from CAR-T-induced CRS suggests parallels to the COVID-19 inflammatory response that would suggest that targeting IL-1β would reduce the inflammatory signaling that mediates lung injury, ARDS, and mortality." (PMID 32655582, 2020). "Patients with COVID-19 have been found to have high levels of proinflammatory cytokines such as IL-6, IL-1β, IP10, and MCP-1." (PMID 33284413, 2020). "In a mouse model of ARDS, which is the main cause of death in COVID-19 patients, CD26 inhibition by sitagliptin alleviated histological findings of lung injury by inhibiting the expression of IL-1β, TNF-α, and IL-6." (PMID 33269102, 2020). "In contrast, IL-1β production was lower in monocytes from COVID-19 patients compared to monocytes from healthy individuals, although this was not related to disease severity." (PMID 32943497, 2020). "Such cocktails are intended to tackle the release of pro-inflammatory cytokines IL-1β and IL-6 mediating lung and tissue inflammation, fever, and fibrosis, as they are supposed to be responsible for the emergence of COVID-19." (PMID 33692684, 2020). "We found statistically significantly higher values of IL–1Ra and IL–1β in the COVID-19 group." (PMID 40217938, 2025). "Escalating concentrations of recombinant spike can activate human lung macrophages, triggering the production of proinflammatory cytokines that mirror the “cytokine storm” signature observed in clinical COVID-19 cases (IL-2, IL-4, IL-6, IL-1β, IL-8, IFN-γ, TNF-α, and CXCL10)." (PMID 41012643, 2025). "In addition, monocytes from severe COVID-19 patients spontaneously secrete IL-1β when incubated in vitro, a response that is reversed upon treatment with an IL-1β antagonist." (PMID 40788382, 2025). "Evidence so far supports that pyroptosis and subsequent IL-1β signaling play an important role in mediating COVID-19 disease pathology and can contribute to COVID-19 disease severity through multiple mechanisms, including lung immunopathology, systemic inflammation, and thrombosis." (PMID 41011440, 2025). "The SARS-CoV-2 spike (S) protein, known for its role in binding with the cell surface receptor ACE2, has been shown to activate the NLRP3 inflammasome and trigger IL-1β release from both macrophages and microglia derived from COVID-19 patients and healthy donors through TLR2-mediated signaling." (PMID 41011440, 2025). "Specifically, higher levels of IL-1β, IL-6, IL-8, IL-10, IL-18, and TNFα have been found in patients with severe disease and complications, such as acute respiratory distress syndrome (ARDS), which are the main cause of mortality in COVID-19." (PMID 40788382, 2025). "Results: showed statistically significant higher values of IL–1Ra and IL–1β in the COVID-19 group." (PMID 40217938, 2025). "Cytokines such as TNF-α and IL-1β are well known for their proinflammatory effects on the endothelium and may play a significant role in vascular dysfunction in COVID-19." (PMID 40495032, 2025). "In addition to the critical role of IL-1β, IL-6 levels have also been shown to correlate with poor prognosis in COVID-19 patients." (PMID 41233351, 2025). "Of the tested inflammatory cytokines/chemokines, only a few significant associations were found with COVID-19 severity: lower levels of IL-1β, IL-33 together with significantly higher levels of IL-18 were found in women with moderate/severe COVID-19 as compared to asymptomatic/mild cases." (PMID 40303405, 2025). "So, if these inflammatory cytokines are critically involved in severe COVID-19, the results from our studies using gene targeted mice indicate a disconnect between the processing and release of IL-1β and IL-18 from inflammasomes, caspases-1/11/12 and pyroptosis." (PMID 40016339, 2025). "Previous studies have already shown that individuals with COVID-19 had high levels of some inflammatory mediators in more severe cases of the disease, such as C-reactive protein, D-dimer, bilirubin, urea, and IL-1β, IL-6, IL-8, IL-10, IL-18, IFN, TNF-α cytokines." (PMID 39861879, 2025).
COVID-19 (continued). "Additionally, the A allele in IFNAR2 rs2236757 was associated with increased IL-1β and IL-12 but decreased IFN-α concentrations in pediatric COVID-19 cases." (PMID 40066463, 2025). "Specifically, the dysregulation of key cytokines like IL-6, TNF-α, and IL-1β during COVID-19 may directly interfere with thermoregulation, contributing to a diminished febrile response in CAM patients with prior COVID-19 infection." (PMID 40315194, 2025). "A reverse assessment in a case–control study of COVID-19 showed increased salivary IL-6 measured at two time points in individuals with both COVID-19 and periodontitis, while periodontitis was associated with elevated salivary levels of RANKL and IL-1β." (PMID 41463036, 2025). "To assess the efficacy of anti-IL-1β therapeutics in our severe COVID-19 mouse model, we administered a single dose of IL-1β-neutralising monoclonal antibodies, analogous to the clinically used human antibody Canakinumab, to 10- to 12-week-old WT mice on the day of infection with P21." (PMID 40016339, 2025). "Moreover, cytokine release syndrome characterized by TNF-α, IL-6, and IL-1β was associated with disease severity and, higher levels of IL6 were more predictive for COVID-19 mortality." (PMID 40121473, 2025). "Moreover, patients with severe COVID-19 and poor prognosis have lower levels of IL1B, IL2, and IL8 compared to those with favorable outcomes." (PMID 41155463, 2025). "A recent scoping review suggests that periodontitis and COVID-19 may independently raise serum levels of IL-1β, IL-6, and TNF-α in the same individual." (PMID 41463036, 2025). "Furthermore, in severe cases of COVID-19, elevated levels of IL-1β and IL-6 cytokines have been observed." (PMID 40072090, 2025). "Here we show that human blood monocytes can effectively sense SARS-CoV-2, and subsequently respond by substantial upregulation of the proinflammatory cytokines TNF, IL-1β and IL-6, which comprise the core hyperinflammatory signature seen in severely ill COVID-19 patients." (PMID 39963132, 2025). "The spike protein has been shown to trigger prolonged expression of cell adhesion markers and the release of various cytokines and chemokines, such as interleukin-6 (IL-6), tumor necrosis factor-alpha (TNF-α), and interleukin-1β (IL-1β), which are commonly observed in severe COVID-19 cases." (PMID 41012643, 2025). "IL-18, IL-1β, and IL-23 have been correlated with arginine biosynthesis in COVID-19." (PMID 41002992, 2025). "Profiling serum samples from COVID-19 patients of varying severity showed strong correlations between metabolites and pro-inflammatory cytokines/chemokines, including IL-6 and IL-1β, highlighting a regulatory interplay between arginine, tryptophan, purine metabolism, and hyperinflammation." (PMID 41002992, 2025). "COVID-19 patients displayed elevated levels of IL-1β, IL-6, and TNF." (PMID 38392902, 2024). "Whether S protein-induced IL-1β production represents the large proportion of whole IL-1β production in macrophages and IL-1β production affects cytokine activation in COVID-19 patients remains unknown." (PMID 38133713, 2024). "Attenuating the NLRP3 inflammasome pathway by VitD3 was accompanied by a decrease in IL-1β, IL-6, IL-17, and D-dimer, reduced hyperinflammation of severely infected COVID-19 patients, as well as correlated with enhanced type I IFN signaling and reduced disease severity." (PMID 38748756, 2024). "Serum IL-1β was increased in all COVID-19 patients compared to healthy subjects as was IL-1Ra." (PMID 39882243, 2024). "Contrary to other data, IL-1β production was impaired in critically ill patients, indicating that a robust IL-1β response might be pivotal for containment of COVID-19." (PMID 38474725, 2024). "IL1B has been related to severe COVID-19 and has also been observed at higher levels in men." (PMID 39590591, 2024). "The cytokine triad of IL-1β, IL-6, and TNF is associated with the post-acute sequelae of COVID-19." (PMID 38932387, 2024).
COVID-19 (continued). "In addition to other pro-inflammatory cytokines, such as Tumor necrosis factor α (TNFα) and IL6, IL1β is also related to COVID-19 pathogenesis." (PMID 39346556, 2024). "IL-6 and IL-1β are pivotal targets of antirheumatic agents, and there is evidence that blocking the IL-6 receptor can reduce lung involvement and acute cardiovascular complications in patients with COVID-19 by inhibiting the systemic inflammatory response." (PMID 38455049, 2024). "Research also indicates that Th17 differentiation is closely related to COVID-19 75, so it can be inferred that CD1C and IL1B may influence the occurrence and development of COVID-19 through the Th17 differentiation pathway." (PMID 39622956, 2024). "Previous studies documented that in vitro blockade of PD-1 could almost normalize the immune expression of IL-1β, IL-1RA and IL-8 levels among patients with COVID-19 and restore T cell function, thus recovered the immune abnormalities to normal." (PMID 38493138, 2024). "Single-cell analysis of bronchoalveolar lavages from critical COVID-19 patients revealed the abundance of inflammatory IL-1β-secreting myeloid cells, which could be involved in lung damages." (PMID 38715114, 2024). "In addition to inhibition of the TNFα, IL-1β and IL-6 induced NF-κB activation, several COVID-19 drugs inhibit the NF-κB activation through disrupting the crosstalk signaling, such as MAPK(JNK/ERK/p38), ANG II-AT1R and ACE2-MAS signaling pathways." (PMID 37872376, 2024). "Therapeutic interventions targeting IL-18 and IL-1β signaling pathways are being studied to alleviate cytokine-driven pathological processes and are expected to improve the clinical prognosis of patients with COVID-19." (PMID 38399989, 2024). "In cases of severe COVID-19, as opposed to moderate instances, there is a notable association between elevated IL-1β levels and phenomena such as hypercoagulation and disseminated intravascular coagulation." (PMID 39518964, 2024). "Interestingly, COVID-19 PMNs produced less IL-1β than HC PMNs upon exogenous inflammasome activation primed by either LPS or IFN-I, while SARS-CoV-2 particles did not have any effect on PMN inflammasome activation." (PMID 39172744, 2024). "Circulating IL-1β and s-uPAR levels were high in the 5G5G COVID-19 patient group." (PMID 39281671, 2024). "Drugs that target the signaling of IL-1β, including IL-1β antagonist (canakinumab) and IL-1 receptor antagonist (anakinra), might be advantageous in treating COVID-19 CS." (PMID 37742314, 2024). "Although IL-1β and IL-18 levels in the plasma and lungs correlate with severe COVID-19 (5, 7, 33, –, 35), whether these inflammatory cytokines restrict viral replication and the consequence of inflammasome activation in the lung have not been clarified." (PMID 39240187, 2024). "Furthermore, autoimmune diseases can be triggered by COVID-19 in genetically predisposed patients, following the activation of an aberrant immune response by the cytokine cascade (TNF-α, IL-6, IL-1β, IL-17, and IL-18) induced by SARS-CoV-2." (PMID 38707102, 2024). "The results presented in our study are a proof of principle that the expression of IL-1β, IL-6 and IL-8 genes, coding key proteins of the COVID-19 “cytokine storm”, can be inhibited by aged garlic extract (AGE) and the AGE bioactive compound S-allyl-cysteine (SAC)." (PMID 39770027, 2024). "In our investigation, we discerned that the levels of S1RBD IgG, along with cytokines IL-6, IL-6R, TNF-α, IL-10, and IL-1β, were markedly elevated in the individuals who received two or three doses of the mRNA COVID-19 vaccine compared to those who received a single dose." (PMID 38932387, 2024). "Moreover, as a pathogen, COVID-19 can trigger a cytokine release syndrome, characterized by elevated levels of inflammatory cytokines, including IL-1β, interleukin 1 (IL-6), interleukin 12 (IL-12), IFN-γ, and TNF-α." (PMID 38287388, 2024).